BRCA1 (BRCA1 DNA repair associated)
Diseases named in the same sentence as BRCA1 in open-access papers (continued):
Sharing a sentence is not in itself a finding about the gene and the disease.
ovarian carcinoma (continued). "As such, in addition to BRCA1/2, other genes in the HR repair pathway, which may provide information for more complete ovarian cancer management, should also be analysed in tumour samples." (PMID 36011309, 2022). "The same results were observed in BRCA1/2 wild-type ovarian cancer cell lines." (PMID 36291176, 2022). "BRCA1 and BRCA2 mutation carriers face an elevated lifetime risk of developing ovarian cancer." (PMID 35668475, 2022). "In addition, the inhibitory effect of 8-CPT-cAMP on BAX protein accumulation was similar to that of dobutamine on the IR-treated BRCA1 knock-down ovarian cancer cells." (PMID 35517499, 2022). "The methylation status of the white blood cell Brca1 promoter could be a predictive biomarker of ovarian cancer." (PMID 36430332, 2022). "Higher percentages of altered FANC genes have been found in HNSCC patients unaffected by FA, as well as in various cancer types, both sporadic and hereditary: among them, breast and ovarian cancer with mutations occurring most likely in FANCA, FANCS/BRCA1, and FANCD2/BRCA2 genes." (PMID 35954197, 2022). "Latest research studies demonstrated that a general testing of ovarian cancer patients for the presence of BRCA1/2m could be useful in planning anticancer therapy." (PMID 36533080, 2022). "This indicates that BRCA1 is essential for DNA damage repair, and that the lack of BRCA1 causes dramatic apoptosis in ovarian cancer cells bearing massive unrepaired DNA double-strand breaks." (PMID 35517499, 2022). "A possible cause for such a reduction could be epigenetic silencing via promoter hypermethylation, which has been detected in the BRCA1 gene in 10–20% of ovarian cancers." (PMID 35203410, 2022). "In addition, both the CCLE and cBioPortal database showed a positive correlation between the expression of NUSAP1 and BRCA1 in ovarian cancer." (PMID 35739489, 2022). "Here, we identified a small molecule SN-38, which could inhibit HR repair activity in ovarian cancer cells and verified the synergistic antitumor effects of SN-38 and olaparib combination in BRCA1/2-proficient ovarian cancer cells." (PMID 36267463, 2022). "Nonetheless, the small number of cases in our cohort and the absence of information concerning the methylation profile of both genes are two limitations of our study, that should be surpassed in other future Moroccan studies dedicated to the implication of BRCA1/2 genes in breast and ovarian cancer." (PMID 35986351, 2022). "Assuming that no other shared genetic and familial risk factors besides BRCA1/2 PVs exist between PCa, breast and ovarian cancer, such ascertainment should in principle not introduce ascertainment bias." (PMID 34963702, 2022). "Among the 18 women with ovarian cancer and a BRCA1 or BRCA2 mutation, ten reported a first- or second-degree relative with breast or ovarian cancer (55.5%), and there was only a slight difference between BRCA1 and BRCA2 carriers (54.5% vs. 57.1%, respectively)." (PMID 35382848, 2022). "In this Asian cohort, we found a high rate of BRCA1/2 mutations (40.0%) among those with a family history of breast/ovarian cancer compared with 5.6% among patients with no family history." (PMID 34467476, 2022). "In this systematic review and meta-analysis, the presence of BRCA1/2m was significantly associated with better OS in ovarian cancer patients, but not in other cancer types." (PMID 35909902, 2022). "For example, the three BRCA founder mutations [BRCA1 185delAG (c.68_69del), 5382insC (c.5266dup), and BRCA2 6174delT (c.5946del)] have high carrier frequency (2.17%) in Ashkenazi Jewish population contributing to high risk of breast and ovarian cancer." (PMID 35595529, 2022).
ovarian carcinoma (continued). "In addition to breast and ovarian cancer, an increased risk for prostate cancer in BRCA2 PV carriers as well as pancreatic cancer in both male and female BRCA1/2 PV carriers has been recognized." (PMID 36497436, 2022). "We describe germline whole-exome sequencing (WES) analyses and apply in silico predictive tools of familial ovarian cancer (OC) cases reported clinically negative for pathogenic BRCA1 and BRCA2 variants." (PMID 35456503, 2022). "However, in BRCA1/2-proficient ovarian cancers, PARP inhibitors' therapeutic effects are relatively low." (PMID 36267463, 2022). "Indeed, the alternations of BRCA1/2 have been noted to increase sensitivity to platinum-based chemotherapy in breast, ovarian cancer and PDAC." (PMID 36457017, 2022). "In addition, PKM2 inhibitor Sk also increased Ola-induced γH2AX foci formation and downregulated BRCA1 foci formation in all three ovarian cancer cell lines." (PMID 35280680, 2022). "Patients with ovarian cancer showed the next highest proportion (BRCA1: 4.86%; BRCA2: 3.42%)." (PMID 35420638, 2022). "However, among patients with primary or recurrent ovarian cancer and BRCA1/2 wildtype, especially HRD (-), survival benefits from olaparib or niraparib were relatively limited." (PMID 35466318, 2022). "Ovarian cancer is less common, but hereditary breast and ovarian cancer (HBOC) syndrome accounts for approximately 90% of the hereditary neoplasms and is highly associated with BRCA1/2 mutations." (PMID 36013212, 2022). "OVCAR8 cells are more resistant to PARPi because of their BRCA-proficient phenotype despite heterozygous methylation on the BRCA1 promoter, whereas PEO1 cells harbor a truncated BRCA2 mutation representing ovarian cancers deficient in DNA damage repair mechanisms." (PMID 36324587, 2022). "Moreover, inhibition of DDX39B triggers sensitivity of BRCA1-mutant ovarian cancer cells to chemotherapy drugs such as platinum and PARPi." (PMID 35832557, 2022). "Contrarily, a study showing very low mutation frequencies for BRCA1/2 included only unrelated index cases with or without a family history of breast and/or ovarian cancer reducing the likelihood of detecting variants in these genes." (PMID 35451682, 2022). "Besides BRCA1 and BRCA2, several other inheritable mutations have been identified that increase ovarian cancer risk." (PMID 35159349, 2022). "TILs are elevated in BRCA1-mutated ovarian carcinomas and have been included in a set of histological criteria predicting BRCA1 mutations in HGSCs, although showing only a high negative predictive value." (PMID 36139508, 2022). "However, cAMP generation dramatically increased in the ovarian cancer cells with knock-down of BRCA1 after dobutamine treatment." (PMID 35517499, 2022). "Along with successful validation on patients carrying BRCA1 and BRCA2 mutations, positive effects of PARPi were also observed in patients without BRCA mutations with high-grade serous or poorly differentiated ovarian carcinoma or TNBC." (PMID 36499000, 2022). "Interestingly, BRCA1 and BRCA2 mutations are responsible for the development of about 90% of all ovarian cancers." (PMID 35740092, 2022). "Women who test positive for an inherited pathogenic/likely pathogenic gene variant in BRCA1, BRCA2, PALB2, CHEK2 and ATM are at an increased risk of developing certain types of cancer—specifically breast (all) and epithelial ovarian cancer (only BRCA1, BRCA2, PALB2)." (PMID 35681696, 2022). "Therefore, clearly both BRCA1 and BRCA2 are susceptible to mutations and play a large role in the pathogenesis of breast and ovarian cancer." (PMID 35740092, 2022). "Moreover, BRCA1 and BRCA2 mutation carriers have risks of 60% and 55%, respectively, for developing ovarian cancer." (PMID 36140723, 2022). "Hereditary mutations in the BRCA1 and BRCA2 genes are risk factors for ovarian cancer." (PMID 35300046, 2022).
ovarian carcinoma (continued). "The aim of this study was to define the prevalence and spectrum of BRCA1 and BRCA2 mutations in unselected ovarian cancer patients from the Region of Podkarpacie with the use of NGS, and establish an optimal algorithm for genetic testing of women diagnosed with ovarian cancer from this region." (PMID 35382848, 2022). "Many PARP inhibitors have been developed and approved by the FDA for treating patients with recurrent Platinum-sensitive ovarian cancer, with or without the loss of the BRCA1/2 gene." (PMID 36142803, 2022). "In PARP inhibitors-resistant but BRCA-mutant ovarian cancer cells, both fork protection functions of BRCA1/2 and HR are sequentially bypassed, and cells become increasingly dependent on ataxia telangiectasia and Rad3-related kinase (ATR) for recruitment of RAD51 onto DSB and stalled forks." (PMID 35886427, 2022). "For example, LoF variants in the BRCA1 gene are strongly correlated with risk for breast and ovarian cancer, yet BRCA1 does not show evidence of constraint for LoF variation, as the phenotype presents post‐reproduction and also is of lower penetrance in males." (PMID 34859531, 2022). "Remarkably, BRCA1 and BRCA2 preserve genomic stability and inhibit tumorigenesis by fostering DSBs repair via the homologous recombination (HR) system and are often mutated in hereditary breast and ovarian cancers." (PMID 36428727, 2022). "Due to the challenges associated with treating ovarian cancer, much effort has been devoted to identifying new therapeutic approaches for the disease, including recent promising results for PARP inhibition for patients with BRCA1/2 mutations." (PMID 36077825, 2022). "Germline mutations in the BRCA1 and BRCA2 genes predispose persons to breast and ovarian cancer." (PMID 35918668, 2022). "In addition to the different roles that these genes play, BRCA1 is involved in other functions, such as in onset of breast and ovarian cancer, healthy embryonic development, centrosome replication, and brain size." (PMID 35805026, 2022). "However, as for patients with primary or recurrent ovarian cancer and BRCA1/2 wildtype, especially HRD (-), survival benefits from PARPi were relatively limited." (PMID 35466318, 2022). "As an example, detection of BRCA1/2 alterations in an ovarian cancer patient might guide clinicians to implement a PARP inhibitor chemotherapeutic strategy." (PMID 35740550, 2022). "We aimed to identify the most cost-effective of all prophylactic measures available in Switzerland for women not yet affected by breast and ovarian cancer who tested positive for a BRCA1/2 mutation." (PMID 34767113, 2022). "It was initially unclear how useful the BRCA1 SGE data would be for variant interpretation, chiefly because HAP1 cells had not been used previously as a model for BRCA1 function and lack clear relevance to breast and ovarian cancer." (PMID 38836089, 2022). "Defects in BRCA1 are responsible for the incidences of familial breast and ovarian cancers." (PMID 36232807, 2022). "Therefore, it is urgent to seek novel strategies to optimize PARP inhibitor therapy, such as in combination with other agents for BRCA1/2-proficient ovarian cancer." (PMID 36267463, 2022). "In addition, BRCA1/2, ATM, BRIP1, PALB2, RAD51C, and RAD51D gene mutations are reported to be associated with high risk of ovarian cancers, and from the results of tumor tissue, it is easy to further determine their genetic status." (PMID 35186721, 2022). "Germline pathogenic variants in BRCA1 and BRCA2 cause hereditary breast and ovarian cancer." (PMID 36068545, 2022). "However, multigene panel genetic testing for patients with breast and ovarian cancer now commonly includes DDR genes in addition to BRCA1 and BRCA2, a number of which are considered moderate or low-risk genes." (PMID 35626031, 2022).
ovarian carcinoma (continued). "Breast cancer susceptibility genes 1 and 2 (BRCA1 and BRCA2, OMIM #113705 and #600185, respectively) are the best known, most well established, and highly penetrant genes associated with increased risk of developing breast and ovarian cancers." (PMID 35456488, 2022). "Mutations in BRCA1 and BRCA2 account for up to 90% of familial breast and ovarian cancer cases." (PMID 36246618, 2022). "Therefore, risk-reducing salpingo-oophorectomy (RRSO) or bilateral prophylactic mastectomy can be done to prevent breast or ovarian cancer in BRCA1/2 gene carriers." (PMID 35115620, 2022). "Mutations in BRCA1 and BRCA2 genes are well-established risk factors of breast and ovarian cancer." (PMID 35382848, 2022). "Furthermore, a query of BRCA1- or BRCA2-mutant ovarian cancer patients from The Cancer Genome Atlas revealed that high PTIP expression correlated with better progression-free survival (PFS) compared to low PTIP expression, which correlated with low PFS." (PMID 36568963, 2022). "Notably, a familial history of breast or ovarian cancer was reported in 95 (49.7%) and 24 (32%) patients (BRCA1 and BRCA2, respectively); conversely, personal history of previous cancer was reported in only three (1.1%) patients." (PMID 36011033, 2022). "The aim of this study was to investigate whether quantitation of BRCA1/2 mRNAs in ovarian cancer can provide information beyond the DNA tests." (PMID 35203410, 2022). "The ESMO guidelines 2019 also recommend testing for BRCA1/2 mutations in advanced, non-mucinous ovarian cancer patients (Ovary cancer: INCA." (PMID 35813356, 2022). "Women with a PV in BRCA1 had the lowest median age at ovarian cancer diagnosis, at 53 years of age." (PMID 33926482, 2021). "In 11% of high-grade ovarian carcinomas, BRCA1 expression is silenced by hypermethylation." (PMID 34711195, 2021). "Ovarian cancer patients with a germline (blood) or somatic (tumor) BRCA1/2 gene mutation had the best prognosis compared to non-BRCA1/2 tumors." (PMID 33670893, 2021). "The use of PARP inhibitors has been successful in ovarian cancers in both BRCA1/2 mutated and non-mutated patients." (PMID 34001250, 2021). "BRCA1 is a tumor suppressor protein best known for its role in breast and ovarian cancer." (PMID 34065298, 2021). "The analysis confirmed common gene expression deregulation in BRCA1/2 mutation carrier patients compared to non-carriers both in the breast and ovarian cancers." (PMID 33525353, 2021). "Monoallelic co-deletion of BECN1 and BRCA1 has been reported in 40-75% of sporadic ovarian cancers." (PMID 33670664, 2021). "BRCA1-carriers have a 45–60% chance of developing ovarian cancer." (PMID 34360968, 2021). "In an unselected Australian TNBC patient cohort, where 59% did not have any family history of breast or ovarian cancer, only 9.3% were found to have germline pathogenic BRCA1/2 variants." (PMID 33918338, 2021). "Hereby, we performed hybridization-based target sequencing of BRCA1/2 in 530 ovarian cancer patients from Henan, the central region of China, followed by haplotype analysis of six short tandem repeat (STR) markers in the patients with recurrent mutations to determine their founder effect." (PMID 34046351, 2021). "Although the mutations of BRCA1 and BRCA2 are the most common germline mutations in ovarian cancer, the mutational frequency of BRCA1 is significantly higher in Chinese than in Western (P = 0.0001), while the mutation frequency of BRCA2 is similar between them (P = 0.78)." (PMID 33432021, 2021).
ovarian carcinoma (continued). "In this context, BRCA1/2 analysis on tumor tissues would allow us to detect both germline and somatic alterations and has already become the standard procedure in other cancer types, such as ovarian carcinoma." (PMID 34200245, 2021). "Although breast and ovarian cancer risk increases considerably, not all women with BRCA1/2 mutations develop a neoplasm." (PMID 34552867, 2021). "Though Poly (ADP-ribose) polymerase (PARP) inhibition is at the forefront of BRCA1/2-mutant breast and ovarian cancer therapy, many new exciting targets such as POLQ, RAD52, FANCD2, FEN1, APEX2, and RNF168, appear to have therapeutic potential in pre-clinical studies." (PMID 35008272, 2021). "On the other hand, genomic studies revealed a significantly lower risk of ovarian cancer, both with and without BRCA1/2 mutation carriers, in the statin group (OR 0.60; 95% CI 0.43–0.83; p = 0.002 vs. OR 0.69; 95% CI 0.51–0.93; p = 0.01)." (PMID 34959621, 2021). "Among ovarian cancer patients more than 9% harbored PVs in BRCA1 and BRCA2 genes." (PMID 34326862, 2021). "In addition, analysis of the promoters of BRCA1 and RAD51C, whose methylation has been shown to be associated with HRD in breast and ovarian cancer, revealed that UCS10 and UCS12 displayed RAD51C promoter hypermethylation." (PMID 33021035, 2021). "Germline mutations of the BRCA1 and BRCA2 genes lead to a high lifetime risk of ovarian cancer." (PMID 34207450, 2021). "HR deficiency is most commonly caused by mutations in important DNA repair genes such as BRCA1 and BRCA2, but PARPi also show effect in ovarian cancer patients without BRCA1/2 mutations." (PMID 34069138, 2021). "Rucaparib was first FDA-approved in December 2016 for advanced BRCA1/2-mutant ovarian cancer." (PMID 34945003, 2021). "BRCA1 and BRCA2 are two major high-penetrance breast/ovarian cancer predisposition genes, whose mutations can lead to high risk and early onset of breast and ovarian cancer." (PMID 34572941, 2021). "PARPi have demonstrated synthetic lethality in HR deficient BRCA1/BRCA2 mutant tumors, which led to their approval in platinum-sensitive (with/without BRCA1/2 mutation) ovarian cancer and in germline BRCA1/2 (gBRCA)-mutated metastatic breast cancer." (PMID 33562741, 2021). "Haploinsufficiency of an autophagy gene, BECN1, which is almost always codeleted with BRCA1, may permit tumor initiation and potentiate genomic instability in ovarian cancer." (PMID 33922503, 2021). "Poly-ADP ribose polymerase inhibitor have emerged as exciting new chemotherapy options for women with ovarian cancer, especially for patients with BRCA1 or BRCA2 mutations or non-functional homologous recombination repair pathways." (PMID 34512721, 2021). "Triapine combined with olaparib prevents homologous recombination repair of double strand breaks in wild type BRCA ovarian cancer cells through preventing RAD51 and BRCA1 foci formation as well as preventing BRCA1 from associating with the MRN complex and attenuation of CtIP phosphorylation." (PMID 33520115, 2021). "BRCA1 or BRCA2 mutations are the most prevalent cause of high penetrance inherited breast or ovarian cancers and have been shown to affect patients irrespective of race or ethnicity." (PMID 33669749, 2021). "We show significant correlation of mutations in BRCA1, BRCA2, and RAD51C with ovarian cancer risk." (PMID 33670479, 2021). "The ovarian cancer risk was associated with mutations in BRCA1, BRCA2, RAD51C, and PALB2 but not in the CHEK2 gene." (PMID 33670479, 2021). "BRCA1 negatively affects pro-survival autophagy in ovarian cancer cells." (PMID 33670664, 2021).